TRAF3 (TNF receptor associated factor 3)
Diseases named in the same sentence as TRAF3 in open-access papers (continued):
Sharing a sentence is not in itself a finding about the gene and the disease.
tumor (continued). "Although the primary tumor in TCL1 mouse E31 had a clonal Traf3 mutation, this mutation was not detectable in the tumor from recipient Q82." (PMID 30262843, 2019). "Nonetheless, we found that the Traf3 mutation in E31 led to increased protein levels of TRAF3 in the leukemic cells compared to a Traf3 non-mutated tumor (line C25)." (PMID 30262843, 2019). "Similar to TRAF2 and also consistent with the frequent deletions and inactivating mutations of TRAF3 identified in human B cell malignancies, a tumor suppressive role for TRAF3 in B lymphocytes has been demonstrated by in vivo evidence obtained from mouse models." (PMID 30294322, 2018). "Therefore, distinct tumor suppressive and oncogenic roles of TRAF3 in different cellular contexts have been revealed from studies of both human and mouse models." (PMID 30294322, 2018). "Thus, TRAF3 acts as a tumor suppressor in naïve B cells, but an appropriate and balanced level, neither too high nor too low, of TRAF3 is required to maintain the homeostasis of plasma cells and protect them from tumorigenesis." (PMID 30294322, 2018). "Inhibition of FGFRs is a promising therapeutic strategy, and phase I and II trials are progressing The tumor suppressor TRAF3 has previously been brought forward as a potential target for therapy development as it was inactivated in 20% of the HPV-positive tumors in the TCGA cohort." (PMID 29879932, 2018). "In contrast, we found that PEP005 induced Akt phosphorylation in TRAF3-/- tumor B cells." (PMID 24131623, 2013). "Interestingly, we detected PEP005-induced nuclear and membrane translocation of PKCδ, PKCα and PKCε in TRAF3-/- tumor B cells." (PMID 24131623, 2013). "However, in sharp contrast, AD 198 did not affect the subcellular distribution of PKCδ, PKCε or PKCα in any TRAF3-/- tumor B cell lines examined in this study." (PMID 24131623, 2013). "Thus, the anti-proliferative and apoptosis-inducing effects of AD 198 on TRAF3-/- tumor B cells are mediated through a novel, PKCδ-independent mechanism." (PMID 24131623, 2013). "These cell lines represent naturally occurring TRAF3-/- tumor B cells." (PMID 24131623, 2013). "Interestingly, we found that AD 198 inhibited ERK, p38 and JNK activation, but promoted Akt activation in TRAF3-/- tumor B cells." (PMID 24131623, 2013). "Furthermore, we extended the investigation of AD 198 to TRAF3-sufficient malignant B cells, and found that AD198 also exhibits anti-tumor activity and potently suppresses c-Myc expression in TRAF3-sufficient mouse and human B lymphoma cell lines." (PMID 24131623, 2013). "Interestingly, AD 198 did induce the cleavage of PKCδ at 6 hours after treatment in TRAF3-/- tumor B cells." (PMID 24131623, 2013). "This prompted us to test the possibility that restoration of PKCδ nuclear translocation may have therapeutic potential in TRAF3-/- tumor B cells." (PMID 24131623, 2013). "Furthermore, we found that AD 198 also exhibited potent anti-tumor effects and targeted c-Myc in TRAF3-sufficient mouse and human B lymphoma cell lines." (PMID 24131623, 2013). "Therefore, we speculate that TRAF3 may exert tumor suppressive effects through the regulation of pyroptosis signaling." (PMID 37798663, 2023). "Although we expect that there are multiple gene alterations in tumor cells that could impact Pim2 expression, our results indicate that TRAF3 likely serves as an important regulator to restrain Pim2 expression at both the mRNA and protein levels in normal and malignant B cells." (PMID 31501481, 2019). "However, TRAF3 has other functions that contribute to long-term tumour growth." (PMID 29146913, 2017). "Both poly-I:C and rintatolimod activate TLR3-mediated nuclear translocation of TRAF3 and IRF3, leading to type-1 interferon production and CXCL10 expression, which attract CD8+ T cells for anti-tumor immunity." (PMID 39949780, 2025).
tumor (continued). "Meanwhile, Traf3 was found to regulate MHC-I through the NF-κB signaling pathway, promoting T cell-mediated tumor cell killing to promote tumor immunotherapy sensitivity." (PMID 40093909, 2025). "As a result, the combination of PD-L1 blockade and TRAF3 overexpression significantly reduced the tumor burden and prolonged the survival of CT-2A GBM tumor–bearing mice (23 days for PD-L1 mAb mice vs. 40 days for PD-L1 mAb + oeTRAF3 mice)." (PMID 39932808, 2025). "Upregulated miR-494-3p, for instance, represses apoptosis by targeting the PTEN tumor suppressor and promoting PI3K/AKT expression, while upregulated miR-494-3p can promote apoptosis by targeting TRAF3 to attenuate hepatic stellate cell activation." (PMID 38256049, 2024). "In these cancers, the upregulation of OTUD7B promotes the stabilization and activation of TRAF3, estrogen receptor α, and N1ICD, leading to uncontrolled cell growth and tumor formation." (PMID 37371581, 2023). "HCC tumor tissues contain high levels of HMOX1, S100A9, TMC7, TRAF3 and TRIM21, whereas the expression of IL8RAP and RGL4 were higher in the control group." (PMID 37171396, 2023). "Overall, our research has demonstrated that TRAF3 in OC cells is an immunosuppressive modulator that down-regulates MHC class I and IFN-I signaling, limits B-cell activation, and reduces the anti-tumor immunity of B cells." (PMID 37121997, 2023). "Western blot analysis performed on tumor specimens revealed that combined CPT/BTZ treatment triggered enhanced PARP cleavage, TRAF3 up‐regulation, and c‐FLIP down‐regulation, as observed in vitro." (PMID 35789025, 2022). "Further, sodium bromate has been suggested to suppress apoptosis by downregulation of TRAF3, NF-kB and IL1 and to influence macrophage reactivity against tumor cells." (PMID 35386057, 2022). "As TRAF3 is a key regulator of B cell survival and is considered to be a tumor suppressor gene of B lymphocytes, IRF6 was presumed to be a tumor suppressor." (PMID 35443865, 2022). "We performed H&E staining to verify tumor tissues and immunohistochemistry to detect the expression of OTUD7B, TRAF3, NIK, Ki67, MMP9 and IL-2 in the xenografted tissues." (PMID 33198776, 2020). "The in vivo experiment showed that Selene exhibited minimal effects on suppressing ascites and inducing tumor cell apoptosis when TLR4 and TRAF3 were knocked down." (PMID 32802180, 2020). "This study identifies new tumor suppressor genes, LRP1B and TRAF3, with possible interactions with HPV and confirmed the role of TGFBR2 and PTEN in ASCC carcinogenesis." (PMID 29804324, 2018). "Consistent with this diagnosis, some neoplasms of this group also express cytosolic IgG as demonstrated by FACS and immunoblotting of protein extracts of lymphoid tissues from representative TRAF3/BCL2 double-tg mice with this type of lymphoid expansions." (PMID 30687320, 2018). "We purified splenic B cells from LMC or tumor-free young B-TRAF3-/- mice (age: 10–12 weeks; premalignant TRAF3−/− splenic B cells), and then stimulated the cells with various B cell stimuli." (PMID 25200342, 2014). "In vitro anti-tumor activities of AD 198 and PEP005 were determined using TRAF3-/- mouse B lymphoma and human patient-derived MM cell lines as model systems." (PMID 24131623, 2013). "Our findings uncovered a novel, PKCδ-independent mechanism of the anti-tumor effects of AD 198, and suggest that AD 198 has therapeutic potential for the treatment of NHL and MM involving TRAF3 inactivation or c-Myc up-regulation." (PMID 24131623, 2013). "Therefore, TRAF3/ECH1 axis–regulated PUFA metabolism controlled the energy supply on the one hand, and modulated the vulnerability of tumor cell to T cell–mediated cell killing on the other hand." (PMID 39932808, 2025). "The reduction in TRAF3 mRNA levels observed in GBM was further validated using paired tumor and nontumor brain tissues through quantitative reverse transcription PCR (qRT-PCR)." (PMID 39932808, 2025).
tumor (continued). "Specifically, within PAAD, TRAF1 and TRAF3 demonstrated positive correlations with stromal, immune, and estimated scores while showing negative correlations with tumor purity." (PMID 38825674, 2024). "We observed elevated expression NIK along with p52 and RelB (primarily in the nucleus) in mouse tumor tissues expressing the PUM1-TRAF3 fusion protein, regardless of TRAF3 expression." (PMID 39090283, 2024). "HPV+ HNSCC cells in culture with experimental depletion of TRAF3 or CYLD displayed increased expression of the subclass-defining genes, as well as robust radio-sensitization, thus recapitulating both the tumor transcriptional state and improved treatment response observed in patient data." (PMID 37523561, 2023). "In summary, our findings provide novel mechanistic insights into how TRAF3 functions as a critical immune checkpoint in myeloid cells to restrain MDSC expansion, thereby preventing overzealous inflammation and indirectly promoting anti-tumor immunity." (PMID 37207205, 2023). "However, the NF-κB Activity Classifier identified many samples in the NF-κB “active” category that do not follow this clear-cut pattern, in particular identifying that simultaneous shallow deletion of TRAF3 and CYLD in a tumor correlated with NF-κB activity." (PMID 35634245, 2022). "Besides, the combination treatment also significantly increased the mRNA levels of TRAF3 and GADD45A and the protein levels of TNFα, TRAF3 and GADD45A in the tumor tissues of these mice." (PMID 34025421, 2021). "High expressions of BRD8, TRAF3, and KITLG were related to hyperfunction of receptors in tumor or immune cell populations, which could in turn influence the survival of patients." (PMID 33790969, 2021). "It is thus perhaps not surprising that TRAF3 has been revealed as an important tumor suppressor in B cells." (PMID 30319624, 2018). "Furthermore, HCMV deubiquitinase acquires pro-tumor functions by inhibiting PRR-mediated type I interferon via deubiquitination of TRAF6, TRAF3, IRAK1, IRF7 and STING." (PMID 28981114, 2017). "Collectively, our data demonstrate that AD 198 but not PEP005 induces rapid apoptosis in TRAF3-/- tumor B cells." (PMID 24131623, 2013). "Taken together, our findings suggest that AD 198 induces the apoptosis of TRAF3-/- tumor B cells not through the translocation or activation of its known target PKCδ, but through a distinct novel mechanism." (PMID 24131623, 2013). "Collectively, the present results suggest that when tumor-derived mutant TRAF3 becomes resistant to receptor-mediated degradation, stabilization of cellular NIK levels is controlled by TRAF3 degradation-independent mechanisms to regulate NF-κB2 activation in B cells." (PMID 24391649, 2013). "NFKB is activated TRADD-, TRAF3- and FADD-dependently and also plays a key role in the survival of tumor cells by inducing expression of anti-apoptotic genes such as Bcl2, Bcl2l1, vascular endothelial growth factor (VEGF), and X-linked inhibitor of apoptosis (XIAP)." (PMID 19077262, 2008). "Importantly, TRAF3’s tumor-suppressive effects were independent of its canonical role in modulating NF-κB signaling." (PMID 40166928, 2025). "This selective activation suggests targeting TLR3/TRAF3/IRF3 without activating NFκB could improve cancer immunotherapy by boosting anti-tumor immunity while minimizing immune suppression." (PMID 39949780, 2025). "Importantly, using microdissected tumor samples and WGS, we detected the highest frequencies of homozygous deletions of the critical tumor suppressor genes CDKN2A, TGFBR2, TRAF3, and potential synthetic lethal target MTAP amongst NPC genomic reports thus far8–14." (PMID 34234122, 2021). "Cytoplasmic TRIM24 reportedly ubiquitinates TRAF3 and facilitates antiviral immunity, a function that may not be relevant to MpBC tumor development and patient survival." (PMID 34508101, 2021).
tumor (continued). "Therefore, it is very likely that PKCδ cleavage induced by AD 198 is a consequence of caspase 3 activation in TRAF3-/- tumor B cells, and is not the initiating signal that triggers the apoptosis." (PMID 24131623, 2013). "Notably, the proportion of GZMB+ cells in the CD8+ T cell population was not obviously altered between the control and oeTRAF3 groups, suggesting that TRAF3 overexpression in GBM cells did not affect the cytotoxicity of CD8+ T cells, but instead affected the susceptibility of tumor cells to T cells." (PMID 39932808, 2025).
cancer (66 papers, 2012 to 2026). A tumor composed of atypical neoplastic, often pleomorphic cells that invade other tissues. "In turn, the knockdown gene expression profile of TRAF3, which is an inhibitor of the NFκB pathway, is associated with better survival and better immune checkpoint blockade response in primary cancer-treated patients having immune checkpoint blockade therapy." (PMID 38375157, 2024). "Traf3 is mutated, though at low frequency, in different cancers of epithelial origin, and low expression is associated with worse outcomes." (PMID 33185187, 2020). "Five mutation hotspots of TRAF3 are identified in more than 5 cancer patients, specifically N16, N285, K286, R310, and R376." (PMID 30294322, 2018). "Whilst for the NF-κB pathway, CYLD and TRAF3 mutations appear to occur at a similar high rate in both cancers (8–11% rates), followed by the same rate of mutations of NLRC5 (6% rates)." (PMID 29933636, 2018). "Approximately 43% (108/253) of the coding-altering mutations of TRAF3 are recurrently detected in at least two cancer patients." (PMID 30294322, 2018). "There are 280 different mutations of TRAF3 detected in human cancers, comprising 90% (253/280) mutations that change the protein sequence of TRAF3 and 10% (27/280) coding silent mutations." (PMID 30294322, 2018). "Intriguingly, lymphocyte-specific TRAF3 transgenic mice also develop plasmacytosis, autoimmunity, inflammation, and cancers, which are likely caused by hyper-responsiveness of B cells to antigens and TLR agonists." (PMID 30294322, 2018). "Another important consideration is whether the metabolic vulnerabilities associated with TRAF3 restoration are unique to GBM or extend to other cancers with similar reliance on PUFA metabolism." (PMID 40166928, 2025). "In our study, we also showed that many genes participate in the different pathways in cancer such as TRAF3, which encode a member of the TNF receptor-associated factor (TRAF) protein family and can associate with TNF receptor (TNFR) superfamily which participates in the signal transduction of CD40." (PMID 31775867, 2019). "Thus, most of the recurrent genetic alterations of TRAF3 identified in human cancers cause complete loss or inactivation of the TRAF3 protein." (PMID 30294322, 2018). "However, it is not well known whether genes with dual TSG and oncogene properties such as TRAF2 and TRAF3 frequently harbor inactivating mutations in cancers with MSI-H." (PMID 34257589, 2021). "In this study, we investigated the prognostic value of the TRAF family members in cancer and identified TRAF3 as a member frequently repressed in GBM due to promoter hypermethylation." (PMID 39932808, 2025). "While the functions of TRAF3 in immune cells, such as T and B lymphocytes, are well documented, its roles in cancer, particularly in GBM, have been underexplored." (PMID 40166928, 2025). "In previous research, TRAF2 and TRAF3 are also the degradation factor of NIK protein and these proteins are frequently deleted and inactive mutated in several cancer types." (PMID 37005661, 2023). "In light of the clinical importance of MDSCs in cancer immunotherapies, we next sought to elucidate how TRAF3 inhibits MDSC expansion." (PMID 37207205, 2023). "Recently, more and more researches have been implied to clarify the relationship between TRAF3 and cancer." (PMID 37798663, 2023). "HECTD3, a member of the third subfamilies of HECT ligases, was validated to target and ubiquitinate caspase-9, c-MYC, and TRAF3 in cancers, already." (PMID 37031183, 2023). "Similar to that observed in B cells, TRAF3 also regulates cell survival and mitochondrial ROS production in macrophages and epithelial carcinoma cells under specific circumstances." (PMID 36776285, 2023). "In carcinoma cells, CD40 recruits TNFR-associated factor (TRAF) proteins (such as TRAF3) to activate pro-apoptotic ASK-1 and facilitate activation of the NOX complex to induce ROS production." (PMID 36291141, 2022).